RNU6-681P (RNA, U6 small nuclear 681, pseudogene)
Gene: Small nuclear RNA gene on chromosome 3 (177,126,017 to 177,126,120, reverse strand). Ensembl gene ENSG00000200882.
Homologues: Orthologues: chimpanzee U6 (99% identical), macaque U6 (89% identical), pig U6 (71% identical). Paralogues in human: RNU6-1260P (86% identical), RNU6-21P (86% identical), RNU6-1103P (85% identical), RNU6-144P (85% identical), RNU6-723P (85% identical), RNU6-746P (85% identical), RNU6-80P (85% identical), RNU6-1145P (84% identical), RNU6-128P (84% identical), RNU6-1316P (84% identical), RNU6-16P (84% identical), RNU6-214P (84% identical), and 1285 more.